CD36 (CD36 molecule (CD36 blood group))
Diseases named in the same sentence as CD36 in open-access papers (continued):
Sharing a sentence is not in itself a finding about the gene and the disease.
breast carcinoma (continued). "Previously, decreased expression of CD36 has been observed in breast cancer and it has also been associated with worse prognosis in CRC patients, lending weight to its role in tumour development." (PMID 30065793, 2018). "Herein, our study indicates that simultaneous inhibition of PI3K/AKT/mTOR signaling and exogenous FAs uptake using a combination of PI3K and CD36 inhibitors might reduce cell proliferation synergistically in anti-HER2 resistant breast cancer with PTEN-loss." (PMID 39920872, 2025). "Given that CD36 has been implicated in driving both ovarian and breast cancers, it could be an attractive target in CD36-expressing tumors." (PMID 36969187, 2023). "In addition, it was reported that breast cancer cells treated with ASC supernatant upregulated their fatty acid receptor CD36, which is associated with migration and invasion." (PMID 36010901, 2022). "More importantly, through the collation of clinical data, this study showed that CD36 was highly expressed on the surface of tumor-associated macrophages in lung cancer and breast cancer patients and was significantly higher than other normal tissue macrophages." (PMID 36387147, 2022). "Interestingly, in breast cancer down-regulation of CD36 expression in cancer-associated fibroblasts is linked with reduced tumor cell proliferation." (PMID 35991116, 2022). "On the contrary, CD36+ fibroblast cause inhibition of breast cancer cell proliferation by secreting proteins like SLIT3, PENK and FBLN1, indicating that CD36+ fibroblasts may play an anti-tumoral role." (PMID 36568966, 2022). "In addition, CD36 was already linked with metastatic potential in breast and melanoma cancer metastasis and as a key element of survival in resistant breast cancer cells." (PMID 34071445, 2021). "Therefore, our study unveils an important role of CD36 in regulation of growth and migration of breast cancer cells and the underlying mechanisms." (PMID 30573731, 2018). "Furthermore, CD36 was shown to play an important role in breast tumorigenesis potentially associated with the observed increase in breast cancer risk found in shift workers." (PMID 25984797, 2015). "Additionally, a study demonstrated that tumor-associated adipocytes could enhance the ability of breast cancer cells to take up FAs and enhance tumor invasiveness by secreting CD36." (PMID 39984452, 2025). "Therefore, in this project, we hypothesized that signaling from CD36+ FBs could cause growth suppression in a subset of breast cancer cell lines." (PMID 34572749, 2021). "CD36 expression is up-regulated in breast cancer patients treated with anti-HER2 therapy (lapatinib, trastuzumab) and is associated with poor prognosis." (PMID 40256431, 2025). "CD36 expression is induced in patients with HER2-positive breast cancer treated with anti-HER2 therapies and is associated with poor prognosis, whereas CD36 knockdown by siRNA promotes cell apoptosis and suppresses tumor growth." (PMID 39920872, 2025). "It has been reported that CD36 is essential for metastasis initiation in oral carcinoma, melanoma, breast cancer, and ovarian cancer, and the expression of CD36 is intimately linked to metastatic initiation and progression." (PMID 39774047, 2025). "Amplification of the CD36 locus is detected in many cancer metastases; mouse cancer models transplanted with CD36 KO breast cancer or melanoma cells showed reduced lung, bone and liver cancer tumor metastases." (PMID 40563926, 2025). "CD36 has been described as contributing to tumor formation and the development of various types of cancer, including breast cancer, gastric cancer, and AML." (PMID 40527069, 2025). "These insights will clarify CD36's dual roles and inform its potential as a therapeutic target tailored to breast cancer subtypes." (PMID 41267927, 2025).
breast carcinoma (continued). "CD36 expression is also reported in different breast cancer cell lines, such as BT-483, HCC2218, MCF-7, and MDA-MB-468, and it is associated with enhancing their proliferative and invasive activities." (PMID 39752516, 2025). "In parallel, CD36 expression is upregulated in lapatinib-resistant breast cancer cells, and targeting CD36 restores sensitivity to lapatinib." (PMID 39984452, 2025). "Based on staining intensity, breast cancer and lymphoma tissues exhibited high CD36 expression, while medium in cervical and liver cancers." (PMID 41550652, 2025). "The paradoxical roles of CD36 in breast cancer—exhibiting both pro‐ and anticarcinogenic effects—warrant careful interpretation of its subtype‐specific functions." (PMID 41267927, 2025). "For example, aggressive breast cancer cells exhibit significantly lower levels of CD36 than aggressive breast cancer cells." (PMID 39984452, 2025). "CD36 expression is correlated with low survival in patients with lung carcinoma, bladder cancer, and luminal breast cancer." (PMID 40527069, 2025). "Studies have shown that CD36 is upregulated in various cancers, including acute myeloid leukemia, breast cancer, colorectal cancer, and gastric cancer." (PMID 41041664, 2025). "To validate these findings, we analyzed two GEO datasets, GSE36693 and GSE62931, confirming that CD36 expression was indeed lower in TNBC compared with other breast cancer subtypes." (PMID 41267927, 2025). "Specifically, we observed that CD36 expression was significantly lower in breast cancer tissues compared with normal tissues, with the lowest expression levels found in TNBC subtypes." (PMID 41267927, 2025). "Cluster of designation 36 (CD36) is considered the predominant membrane protein facilitating FA transport and is overexpressed in HER2-positive breast cancer and associated with enhanced cell proliferation and migration." (PMID 39920872, 2025). "Our data demonstrate that CD36 is consistently downregulated across breast cancer subtypes, with the most pronounced suppression in TNBC, where reduced expression correlates with advanced disease stages and poorer prognosis." (PMID 41267927, 2025). "In the NeoALTTO clinical trial, high expression of CD36 was associated with a poor response to neoadjuvant therapy and an unfavorable prognosis in HER2-positive breast cancer patients." (PMID 40303293, 2025). "The first pathway involves the phosphorylation of STAT3, which binds to the CD36 promoter, inducing its transcription and promoting fatty acid uptake in breast cancer cells." (PMID 40002245, 2025). "Using Kaplan–Meier plotter analysis, we examined the correlation between CD36 expression and breast cancer prognosis." (PMID 41267927, 2025). "In this study, CD36 was highly expressed in anti-HER2 resistant HCC1569 breast cancer cells compared to anti-HER2 sensitive SK-BR-3 cells and the HER2-negative MDA-MB-231 cells." (PMID 39920872, 2025). "In a mouse model of breast cancer, NK cells demonstrated a notable lipid accumulation mediated by CD36 and CD84, which results in the downregulation of perforin- and granzyme-related genes and an inhibitory effector function." (PMID 40002245, 2025). "In the context of HER2-positive breast cancer, genes including ACLY, FASN, CPT1/2, CD36, and SCD1 have been associated with drug sensitivity to targeted therapies 34,35." (PMID 40303293, 2025). "To explore the role of CD36 in breast cancer, we initially analyzed gene expression data from breast cancer patients using the TCGA and GEO databases." (PMID 41267927, 2025). "CD36 expression increased dramatically in breast cancer patients after receiving anti‐HER2 medication." (PMID 40956032, 2025).
breast carcinoma (continued). "BCCs can uptake exogenous monounsaturated FA via CD36, but BCCs are highly dependent on the activity of SCD1 in the absence of exogenous monounsaturated FA, and inhibition of SCD1 and CD36 produces a significant anti-tumor synergy in breast cancer." (PMID 40256431, 2025). "The fatty acid transporter CD36 plays a crucial role in lapatinib resistance in breast cancer; inhibiting CD36 expression reduces fatty acid uptake by lapatinib-resistant breast cancer cells." (PMID 39609317, 2024). "Nobiletin, a flavonoid extracted from citrus peel, was found to have antitumor effects on CD36-dependent breast cancer cells." (PMID 38276607, 2024). "Reducing CD36 expression restored sensitivity to lapatinib in resistant cells and induced inhibition of cell growth in in vivo models of breast cancer." (PMID 39624081, 2024). "Recent studies have shown that CD36 expression promoted the metastasis of human oral carcinoma cells, ovarian cancer cells, gastric cancer cells, pancreatic cancer cells, and breast cancer cells." (PMID 38276607, 2024). "In particular, PA and OA have been implicated in the metastatic initiating potential and migratory behavior of CD36-positive breast cancer cells." (PMID 37377750, 2023). "CD36 expression is increased in many types of cancer, such as acute myeloid leukemia, breast cancer, colorectal cancer, and gastric cancer." (PMID 37684986, 2023). "High expression of CD36 has been observed in diverse cancer types, including liver cancer, breast cancer, colorectal cancer, and gastric cancer." (PMID 38060103, 2023). "Our group previously demonstrated that CD36 mediates the acquisition of resistance to the tyrosine kinase inhibitor lapatinib in HER2+ breast cancer." (PMID 37371076, 2023). "LDL induces breast cancer cell migration that relies on CD36 for mitochondrial metabolism and network remodeling, providing an antimetastatic metabolic strategy." (PMID 37377750, 2023). "Inhibition of CD36 and FABP4 significantly reduces the proliferation, migration, invasiveness, and tumorsphere-forming capacity of breast cancer cells, which is associated with reduced tumorigenicity in a xenograft mouse model." (PMID 38060103, 2023). "Prior reviews have discussed correlations between the Adipocytokine signaling pathway (linked to HubGs CD36 and ACACB) and breast cancer cells, offering novel insights for prevention and treatment." (PMID 37893423, 2023). "CD36 is upregulated in regulatory T cells in breast cancer and melanoma but tends to be downregulated in CRC." (PMID 38072118, 2023). "Human breast cancer cells co-cultured with adipocytes show upregulation of CD36 expression, with fatty acid import into the cytosol or mitochondria." (PMID 38060103, 2023). "ScRNA-seq data of the current study indicated increased MARCO+ and CD36+ macrophage subpopulations with immunosuppressive functions in breast cancer." (PMID 37153595, 2023). "In this study, we identified 8 cDEGs (COL11A1, COL10A1, CD36, ACACB, CD24, PLK1, UBE2C, and PDK4) as breast cancer (BC)-causing HubGs from 3 microarrays and one scRNA-seq dataset by the protein-protein interaction (PPI) network analysis of 46 cDEGs." (PMID 37893423, 2023). "Recent clinical studies have confirmed that higher CD36 expression correlates with poorer outcomes in early-stage HER2+ breast cancer patients undergoing trastuzumab-lapatinib therapy." (PMID 37700339, 2023). "The overexpression of CD36 promotes the progression of solid malignancies such as breast cancer, gastric cancer, glioblastoma and colorectal cancer." (PMID 37014331, 2023). "Clinical data show that CD36+ cells correlate with greater invasion and poor prognosis in several carcinomas, and CD36 inhibition also impairs metastasis in breast cancer-derived tumors and human melanoma." (PMID 37108208, 2023). "CD36 in TAMs mediates FA uptake through S100A4-PPAR-γ axis that promotes tumor growth in a mouse models of breast cancer and fibrosarcoma." (PMID 36686729, 2022).
breast carcinoma (continued). "We showed that coculturing triple-negative or luminal A breast cancer cells with CD36+ FBs in 3D ECM effectively inhibited cancer cell growth." (PMID 36361532, 2022). "There is compelling evidence that FABP4 chaperone protein and CD36/SR-B2 constitute pivotal regulatory factors of fatty acid transport in human cancer and are upregulated in several human cancers, e.g., breast cancer, colon cancer, cervical cancer." (PMID 36012230, 2022). "The effect of RGZ on CD36 in breast cancer angiogenesis is a strategic approach for drug development." (PMID 36114448, 2022). "High fat diet has been shown to boost the metastatic potential in a CD36- dependent manner, while inhibition of CD36 resulted in impaired metastasis in melanoma and breast cancer derived tumors." (PMID 35323656, 2022). "Upon adipocytes co-cultivated with breast cancer cells, the expression of CD36 and FATP1 was elevated compared to adipocytes cultivated alone." (PMID 36428985, 2022). "In another study, intratumoral regulatory T cells in breast cancer patients exhibited increased CD36 expression; however, blocking CD36 inhibited tumor growth." (PMID 35625074, 2022). "CD36 plays an important role in the process of metastasis and correlates with poor prognosis in oral cancer, lung squamous cancer, bladder cancer, and breast cancer." (PMID 35884514, 2022). "This evidence demonstrates the role of CD36 in cellular characteristics that are key for breast tumor progression and highlights a special influence of adipocytes in the EMT and stemness induction in CD36+ breast cancer cells." (PMID 36568966, 2022). "In agreement, CD36 knock-down reduced the proliferative, migratory, and invasive characteristics of breast cancer cells and reduced the expression of EMT-regulating transcription factors, as well that of EMT and stemness markers." (PMID 36568966, 2022). "During the intake of exogenous fatty acids, over-expression of CD36 can be observed in cancers, such as breast cancer, stomach cancer, and ovarian cancer." (PMID 35743814, 2022). "Among them, CD36 is reported to be highly expressed in various malignancies, including breast cancer, ovarian cancer, and gastric cancer." (PMID 36052242, 2022). "Then, we identified SLIT3, FBLN-1, and PENK as active protein ligands secreted from CD36+ FBs that induced growth suppression of MDA-MB-231 breast cancer cells and determined their minimum effective concentrations." (PMID 36361532, 2022). "In breast cancer, CD36 is highly expressed, and some studies have found that CD36 plays an essential role in cancer progression, migration and metastasis by regulating cell cycle and ERK1/2 signaling." (PMID 35216285, 2022). "Co-culturing breast cancer cells with adipocytes significantly increase CD36 expression, CD36 activates STAT3 and ERK1/2 signaling pathways to induce the gene expression of EMT and stem cell traits." (PMID 35899119, 2022). "Compared to peripheral blood mononuclear cells, intratumoral Tregs from patients with melanoma, breast cancer, and non-small-cell lung carcinoma express high amounts of the fatty acid scavenger receptor CD36." (PMID 34983949, 2022). "They found that Tregs in breast cancer expressed high levels of the fatty acid transporter CD36, which has also been demonstrated in other cancers." (PMID 36387147, 2022). "The clinical presence of CD36+ metastasis-initiating cells correlates with a poor prognosis, but CD36 inhibition impairs cellular metastasis, at least in human melanoma- and breast cancer-derived tumors." (PMID 35892853, 2022). "Overexpression of CD36 was reported in tumor metastasis of various cancers (e.g., breast cancer, ovarian cancer, pancreatic ductal adenocarcinoma)." (PMID 36506940, 2022). "In the mouse model of breast cancer CD36 regulates TME via clearance of tumor-derived miR-375, a prominent tumor suppressor." (PMID 36686729, 2022).
breast carcinoma (continued). "As CD36 has an active role in FA import, it seems to be participating in energy metabolism reprogramming in breast cancer cells." (PMID 36568966, 2022). "The exception is the AKT/ERK1/2/STAT3 pathway, which is affected by CD36 silencing or blocking in breast cancer, HCC, leukemia, GBM, cervical cancer, and CRC." (PMID 36568966, 2022). "Four-fold down-regulation of the platelet glycoprotein Cd36 was observed in mouse macrophages of breast cancer bone metastases samples." (PMID 35388653, 2022). "In MCF-7 breast cancer cells stimulated with PA, Nobiletin mimics the effects of CD36 knock-down, decreasing tumorsphere formation, the expression of stemness markers (SOX2, OCT4 and NANOG), STAT3 phosphorylation, and NF-kB activation." (PMID 36568966, 2022). "to a treatment strategy where ER+ breast cancer patients are administered simultaneously with tamoxifen and CD36 inhibitors to overcome tamoxifen resistance." (PMID 35448537, 2022). "Yet, it is intriguing to observe high expression of CD36 in tamoxifen-resistant MCF-7 breast cancer cells and its inhibition led to restoration of tamoxifen-mediated growth inhibition." (PMID 35448537, 2022). "On the other hand, the fatty acid transporter CD36 has been found to promote tumor metastasis under high nutrient conditions in various cancer types, such as oral cancer, breast cancer, and melanoma." (PMID 35259022, 2022). "Previously, we showed that coculturing triple-negative or luminal A breast cancer cells with CD36+ fibroblasts (FBs) in a three-dimensional extracellular matrix induced their growth suppression or phenotypic reversion, respectively." (PMID 36361532, 2022). "For example, CD36 is coexpressed with the stemness markers CD44+/CD133+/ALDH+ in breast cancer, with CD44bright in OSCC, and with CD44+/CD133+/ITGA6+ in GBM." (PMID 36568966, 2022). "Hereby, adipocytes profoundly influence the invasiveness and metastasis of malignant breast cancer by inducing metabolic reprogramming by elevating the expression of CD36, accompanied by accelerated FA uptake." (PMID 36428985, 2022). "In a HER/neu mammary tumor mouse model, CD36 expression is induced by anti-HER2 therapy (lapatinib or trastuzumab) and mammary gland-specific cd36 knockout suppresses tumor growth and extends survival." (PMID 36568966, 2022). "Fatty acid translocase/CD36 is a key membrane glycoprotein involved in importing adipocyte-released fatty acid into breast cancer cells." (PMID 34561446, 2021). "In contrast, Apo A1, CETP, and CD36 protein concentrations were broadly similar between breast cancer and control women." (PMID 34503091, 2021). "In this study, we found that CD36 expression increased, following co-culturing breast cancer cells with hADS, and in the clinical data of breast cancer patients." (PMID 34561446, 2021). "Increased expression of LPL occurs in breast cancer, non-small cell lung cancer, and chronic lymphocytic leukemia, with breast cancer also exhibiting increased CD36 expression." (PMID 33946927, 2021). "FATP1 and CD36 are found as putative targets to disturb the smuggling of lipids between CAFs and breast cancer cells." (PMID 34888248, 2021). "Co-culturing human adipocytes and breast cancer cells increased CD36 expression, with fatty acid import into breast cancer cells." (PMID 34561446, 2021). "Collectively, these results indicate that CD36 upregulation enhances the proliferative, migratory, and invasive capabilities of breast cancer in adipocyte-breast cancer cell interaction." (PMID 34561446, 2021). "In line with this, inhibition of CD36 reduced lipid droplet accumulation and weakened the aggressiveness of breast cancer cell lines." (PMID 35071325, 2021). "Contrary to decreasing breast cancer cell proliferation and aggressiveness, CD36 expression reportedly also has a tumour suppressive role." (PMID 34561446, 2021). "In adipocyte-breast cancer cell interaction, CD36 plays a role in reprogramming metabolism, with a shift towards enhanced FAO11,13." (PMID 34561446, 2021).